CD4 (CD4 molecule)
Diseases named in the same sentence as CD4 in open-access papers (continued):
Sharing a sentence is not in itself a finding about the gene and the disease.
chronic hepatitis C (44 papers, 2007 to 2026). "Chronic hepatitis C patients show higher expression of CD4+ Th lineage-associated cytokines, with the exception of IL-21." (PMID 30443787, 2019). "Previous studies on chronic hepatitis C have found that human CD4+ CD25+ T cells can cause pronounced and sustained inhibition of CD8+ T cell proliferation." (PMID 21851644, 2011). "Having established their baseline function and phenotype in healthy donors, we next addressed whether CD161+CD4+ T cells were associated with intrahepatic infiltrates during chronic hepatitis C infection." (PMID 23181064, 2012). "The role of increased frequencies of CD4+ Tregs has been extensively studied in chronic hepatitis C,36, 37, 38, 39, 40 whereas reduced CD4+ Tregs in PSC is a relatively new finding." (PMID 38607233, 2024). "LTA inhibits the proliferation of CD4(+) T-cells in a FoxP3(+) Treg-dependent manner in patients with chronic hepatitis C, suggesting that LTA acts on FoxP3." (PMID 33671013, 2021). "The presence of CD4+ T‐cell co‐stimulation modules was correlated with interferon and ribavirin combination treatment for chronic hepatitis C virus infection." (PMID 34841705, 2021). "The rate of CXCR5+CD4+ T cells is markedly higher in chronic hepatitis C patients than in healthy controls." (PMID 30443787, 2019). "The expression of CD4+CD25+ forkhead box protein (FOXP) 3+ Tregs within a CD4+ T cell population was detected in the peripheral blood obtained from patients with chronic hepatitis C and from healthy control subjects using flow cytometry." (PMID 24944616, 2014). "CD4+CD25+FOXP3+ Tregs accounted for 14.24±1.33% of the CD4+ T cells in the peripheral blood of patients with chronic hepatitis C, which was higher than that of the healthy control subjects (5.62±1.21%; P<0.001)." (PMID 24944616, 2014). "CD4+CD25+FOXP3+ Tregs accounted for 14.24±1.33% of CD4+ T cells in the peripheral blood obtained from patients with chronic hepatitis C, which was higher than that of the healthy control subjects (5.62±1.21%; P<0.001, Table I)." (PMID 24944616, 2014). "The PD-1 expressing CD4+ T-cells (P = 0.012) or CD8+ T-cells (P = 0.004) were significantly higher in chronic hepatitis C patients than those in healthy controls at baseline." (PMID 24709775, 2014). "Recently we succeeded in establishing HCV core-specific CD25+CD4+ T cells clones from patients with chronic hepatitis C, which to some extent seem to reflect functions and phenotype of HCV-specific adaptive CD4+ Tregs." (PMID 22848715, 2012). "This study used differently polarized CD4+ T cell clones from patients with chronic hepatitis C to analyse the effects of ribavirin on T cell functions in vitro." (PMID 22848715, 2012). "Identified risk factors for developing hepatotoxicity with nevirapine are female gender, chronic hepatitis C/B virus coinfection, a CD4 count <250 cells/mm3 in women and <400/mm3 in men, and abnormal baseline transaminase levels." (PMID 21455432, 2011). "Several studies demonstrate that patients with chronic hepatitis C have an impaired adaptive immunity with dysfunctional CD4+ T cells, CD8+ T cells and natural killer (NK) cells, atypical memory B cells, and diminished mucosal-associated invariant T (MAIT) cell compartment." (PMID 37238990, 2023). "However, lowered T cell numbers, especially the CD4+ subset, have also been reported during aging, and after chronic hepatitis C infection and MS." (PMID 36232808, 2022). "Therefore, during chronic hepatitis C, effector T cells become exhausted over time and show an impaired antiviral activity while CD4+ regulatory T cells (Tregs) accumulate in the liver." (PMID 30583555, 2018). "The percentage of CD4+CD25+FOXP3+ Tregs was greater in patients with chronic hepatitis C than in the healthy control subjects and CD4+CD25+FOXP3+ Tregs were able to inhibit the response of CD8+ T lymphocytes to various virus antigens, thus, promoting chronic HCV infection." (PMID 24944616, 2014).
chronic hepatitis C (continued). "Patients with chronic hepatitis C may produce certain factors that stimulate the hyperplasia and maturity of CD4+CD25+FOXP3+ Tregs." (PMID 24944616, 2014). "The present study demonstrated that the percentage of CD4+CD25+FOXP3+ Tregs in CD4+ T cells obtained from the peripheral blood was greater in patients with chronic hepatitis C than in the healthy control subjects, indicating that Tregs are overexpressed in HCV infected patients." (PMID 24944616, 2014). "With our cloning strategy we obtained 24 CD4+ T cell clones from 12 patients with chronic hepatitis C, which - based on their cytokine profiles and proliferative responses - could definitely be classified as Tregs, TH2 cells or TH1 cells, respectively." (PMID 22848715, 2012). "To determine the direct influence of ribavirin on differentially polarized CD4+ T cells from chronic hepatitis C, we stimulated our Treg, TH1 and TH2 clones with anti-CD3/anti-CD28 in the presence of variable concentrations of ribavirin and measured their proliferation and cytokine responses." (PMID 22848715, 2012). "Furthermore, old age, high eGFR, low serum creatinine, low CD4 counts, high HIV viral load, concurrent use of nephrotoxic drugs, presence of chronic hepatitis C, and smoking were associated with TDF-related renal dysfunction." (PMID 21799928, 2011). "However, evaluation of such CD4+ T-cell responses in chronic hepatitis C is extremely difficult as they are typically described as ‘weak’ or ‘absent’ in persistent infection." (PMID 20107020, 2010). "Long-term viremia may eventually be associated with a decline in tetramer+ cells; this, however, seems to be much slower than the decline in HCV-specific CD4+ T cells that we observed in patients with evolving chronic hepatitis C." (PMID 17653276, 2007). "The aim of the present study was to investigate the distribution of CD4+CD25+ regulatory T cells (Tregs) in the peripheral blood of patients with chronic hepatitis C; in addition to identifying whether the distribution of CD4+CD25+ Tregs predicts the efficacy of antiviral therapy for HCV." (PMID 24944616, 2014). "Importantly we did not observe escape mutations in this key CD4+ T cell epitope in patients with evolving chronic hepatitis C." (PMID 17653276, 2007). "CD4+CD25+ regulatory T-cells are thought to contribute to the impaired immune response in CHB and chronic hepatitis C patients." (PMID 38398102, 2024). "In chronic hepatitis C (CHC), characterized by exhaustion of T-cell function, increased frequencies of double-positive (DP) (CD4+CD8+) cells are present in peripheral blood." (PMID 37408280, 2023). "HCV CD4+ and CD8+ specific T cells responses are functionally impaired during chronic hepatitis C infection." (PMID 34242330, 2021). "In rare cases of spontaneous HCV elimination (up to 20–30%), the emergence of numerous specific CD4+ T cells and higher levels of interleukin (IL)-2, IFN-γ, TNF-α, and IL-17A are observed compared to patients with chronic hepatitis C." (PMID 30443787, 2019). "There is strong evidence for the important role of both virus-specific CD4+ and CD8+ T cells in HCV virus clearance as well as in mediating liver cell damage in chronic hepatitis C infection." (PMID 20727132, 2010). "In chronic hepatitis C, a decrease in IL-2 appears to be chiefly responsible for the lack of activation of virus-specific CD4+ T cells." (PMID 34832674, 2021). "We assessed whether the impaired functionality of HCV-specific CD4+ and CD8+ T cells manifested by reduced T helper 1 cytokine production (IL2 and IFN-Ɣ) during chronic hepatitis C is restored upon HCV clearance with DAA treatments." (PMID 34242330, 2021). "We studied CD4+ and CD8+ T cell and CD19+ B cell apoptosis in 104 HIV-positive patients (56 were also HCV-positive) and in 22 HCV/HIV-coinfected patients treated for chronic hepatitis C with pegylated interferon and ribavirin." (PMID 24098405, 2013).
chronic hepatitis C (continued). "Overall the role of Type 17 CD4+ T cells in the liver during chronic hepatitis C has not been extensively evaluated." (PMID 23181064, 2012). "However, MafB inhibition did not affect CD14+ monocytes-induced CD4+ T cells differentiation in vitro in chronic hepatitis C patients." (PMID 31447817, 2019). "In summary, the increased expression of inhibiting receptors, the lack of function of CD4+ cells, and the increased activity of Tregs all contribute to the impaired function of CD8+ lymphocytes in chronic hepatitis C." (PMID 30443787, 2019). "This interesting observation is in accordance with data indicating that a T-helper (Th) 1 to Th2 shift does not occur in chronic hepatitis C. Further more, IFN alpha alone or in combination with ribavirin acts induces and maintains high rates of significant CD4+ Th 1 response." (PMID 17875206, 2007).
liver cirrhosis (44 papers, 2012 to 2025). "This further underlines the dysfunctional phenotype of CD8+ and CD4+ T cells in patients with compensated liver cirrhosis." (PMID 41028194, 2025). "We have previously shown that appearance of minimal hepatic encephalopathy (MHE), with mild cognitive and motor impairment, in patients with liver cirrhosis is associated with a shift in peripheral inflammation with increased activation of Th17 CD4 lymphocytes and increased plasma levels of IL-17." (PMID 38671534, 2024). "In conclusion, CD8+ and, to a lesser extent, CD4+ T cells from patients with compensated liver cirrhosis show suppressed responsiveness to stimulation with IL-12 + IL-18 compared with healthy individuals." (PMID 41028194, 2025). "Despite the lack of a strong correlation between activated T cells and the proportion of TEMRA CD4+ T cells, CD8+ T cells expressing CD38+ were associated with an increase in TEMRA CD4+ T cells in patients with liver cirrhosis." (PMID 39755990, 2025). "Flow cytometry revealed that CD8+ T cells, but not CD4+ T cells were diminished in patients with decompensated liver cirrhosis and this further resulted in an increased CD4/CD8 T cell ratio in those patients." (PMID 41028194, 2025). "Compared to HCW and unvaccinated individuals, liver cirrhosis patients had significantly depleted T cells, although CD4:CD8 + T cell ratio was normal." (PMID 38280060, 2024). "Gut immune barrier alterations in duodenal tissue samples by T lymphocytes and Th1 cytokines, and pro-inflammatory biomarkers using CD4 Alexa Fluor 488 and IL-2 PE stain, were used to establish their different patterns in liver cirrhosis or hepatic steatosis." (PMID 38473721, 2024). "The participants with T2D and NASH or liver cirrhosis had greater numbers of CD28 − CD57+ senescent CD4+ and CD8 + T cells in their livers than the healthy controls." (PMID 37735474, 2023). "Since the gender distribution, CD4 cell count, and frequency of co-infections and liver cirrhosis were similar in the two groups, these data suggested that the age variable does not significantly affect the kinds of risk factors for talaromycosis." (PMID 34881254, 2021). "Subtyping revealed reduced numbers of CD4+ T cells at all stages of liver cirrhosis and of CD8+ T cells in patients with acutely decompensated liver cirrhosis and ACLF." (PMID 33574809, 2020). "Of note, relative numbers of CD4+ regulatory T cells were significantly higher in patients with compensated/acutely decompensated liver cirrhosis and ACLF in comparison to healthy controls." (PMID 33574809, 2020). "In contrast, CD28 and CD11a were not significantly altered on CD4+ effector T cells and regulatory T cells, whereas ICOS was only upregulated on CD4+ regulatory T cells of patients with liver cirrhosis." (PMID 33574809, 2020). "The present study demonstrated that the number of CD4+ T cells increased rapidly after autologous BMC transplantation in the 12 HIV-infected patients with liver cirrhosis, which was faster in the younger patients as compared with the elderly." (PMID 32520354, 2020). "Isolated FDCs from splenic tissues of HBV-related liver cirrhosis-induced hypersplenism patients were cultured with autologous intrasplenic CD4+ T cells and CD19+ B cells." (PMID 33160362, 2020). "An exceptional expression was observed for the co-stimulatory molecule CD27, which was expressed at significantly lower levels on CD4+ T cells of patients with compensated and acutely decompensated liver cirrhosis." (PMID 33574809, 2020). "To the best of our knowledge, we are the first to disclose the presence of a major interaction between BT, CD4+ T cells and liver cirrhosis." (PMID 28134306, 2017). "The characters and function of CD4+ T cells suggest that they potentially play important roles in the regulation of both BT and liver cirrhosis." (PMID 28134306, 2017). "Among the study sample, 21% presented with liver cirrhosis at enrolment and 12% had a CD4 count < 200/mm3." (PMID 22409788, 2012).
liver cirrhosis (continued). "CD4-positive T cells play a crucial role in the immune response against Pj, and a decrease in these lymphocyte counts has been documented in patients with liver cirrhosis." (PMID 40704273, 2025). "This may further explain the enhanced proliferation of CD8+ and CD4+ T cells observed in patients with decompensated liver cirrhosis, as a replenishment of cells, that have migrated to tissue sites, is necessary." (PMID 41028194, 2025). "We are unable to establish the underlying mechanism for advanced HIV disease resulting in earlier mortality, and advanced liver cirrhosis itself may contribute to changes in CD4 counts." (PMID 37024807, 2023). "A number of co-stimulatory molecules, namely CD40L, OX-40, GITR, and TIM-1 were significantly upregulated on both effector and regulatory CD4+ T cells in patients with liver cirrhosis compared to healthy controls, as well as the T cell activation markers CD69 and CD38." (PMID 33574809, 2020). "We found significantly higher expression of markers of T-cell senescence (e.g., PTPRC, TIGIT, and TNF) and exhaustion (e.g., PDCD1, CTLA4, LAG3, and TNFRSF9) in hepatic CD4+ and CD8 + T cells in participants with NASH or liver cirrhosis than in controls." (PMID 37735474, 2023). "Genes related to senescence (e.g., PTPRC, TIGIT, and TNF) and exhaustion (e.g., PDCD1, CTLA4, LAG3, and TNFRSF9) were highly enriched in CD4+ and CD8 + T cells from the participants with liver cirrhosis." (PMID 37735474, 2023). "Surprisingly, BE from treatment naïve HBV-CLD patients attenuated the expansion of T helper 1 cells (Th1 (CD3+CD4+IFN-γ+) p = .002), and this effect was remarkably predominant in patients with liver cirrhosis compared to HCs (Th1 p = .002, Figure 6aand b)." (PMID 36519342, 2023). "On a functional basis, the capacity of CD4+ and CD8+ T cells to produce pro-inflammatory cytokines upon stimulation was strongly diminished in patients with acute decompensation of liver cirrhosis and ACLF." (PMID 33574809, 2020). "Of note, baseline expression of IFN-γ and TNF-α appeared to be higher in CD4+ and CD8+ T cells of patients with all stages of liver cirrhosis compared to healthy controls." (PMID 33574809, 2020). "The frequency of circulating CXCR5+CD4+ T cells was significantly decreased in HCC patients compared with HBV-relative liver cirrhosis (LC) patients and healthy controls, and the decrease in circulating CXCR5+CD4+ T cells correlated with disease progression." (PMID 25689070, 2015). "In agreement with that, the current study revealed a significant decrease in CD3+ and CD4+ cells in HCV, S. mansoni infected groups, concurrent dually infected individuals and those with liver cirrhosis." (PMID 25066324, 2014). "This was further corroborated by an increased CD4/CD8 T cell ratio in patients with decompensated liver cirrhosis compared to patients without liver cirrhosis." (PMID 41028194, 2025). "In line with this, frequencies of naive CD4+ T cells were also found to be higher in healthy controls compared to those with compensated liver cirrhosis, but not decompensated liver cirrhosis." (PMID 41028194, 2025). "In more detail, we observed that CD8+ but not CD4+ T cells were diminished in patients with decompensated liver cirrhosis further resulting in an increased CD4/CD8 T cell ratio." (PMID 41028194, 2025). "Furthermore, the proliferative capacity, indicated by Ki-67 expression, was significantly elevated in patients with decompensated liver cirrhosis in both CD8+ and CD4+ T cells." (PMID 41028194, 2025). "Taken together, CD8+ T cells, but not CD4+ T cells are decreased in patients with decompensated liver cirrhosis and CD4+ as well as CD8+ T cells are skewed towards a more differentiated phenotype in compensated, but not decompensated liver cirrhosis." (PMID 41028194, 2025).
liver cirrhosis (continued). "Furthermore, high expression of genes related to senescence and exhaustion was identified in CD4+ and CD8 + T cells from the participants with nonalcoholic steatohepatitis or liver cirrhosis." (PMID 37735474, 2023). "The CD4+ T cells and CD4/CD8 ratio in liver cirrhosis is reduced." (PMID 36686655, 2022). "In addition, the phenotype of CD4+ and CD8+ T cells shifted towards activated and exhausted effector-memory and terminally differentiated cells in patients with compensated liver cirrhosis, which was parallelled by an impaired functional response upon stimulation with IL-12 + IL-18." (PMID 41028194, 2025). "Three major T-cell populations were defined on the basis of the expression of marker genes in hepatic CD4+ and CD8 + T cells, which demonstrates the dynamics of hepatic T-cell fate determination related to senescence and exhaustion in the livers of patients with liver cirrhosis." (PMID 37735474, 2023). "However, changes in intestinal CD4+ T cells and their interactions with BT have not previously been explored in liver cirrhosis." (PMID 28134306, 2017). "Therefore, determining the negative control exerted by the CD38 marker in CD4+ T cell differentiation and the mechanism by which this inhibition impacts the control of tumor cells and bacterial infections is critical in patients with liver cirrhosis." (PMID 39755990, 2025). "Indeed, CD4+ and CD8+ T cells of patients with liver cirrhosis in our study showed high expression of pro-inflammatory cytokines at baseline which may contribute to inflammation-induced organ failures, but a lacking on-demand increase in response to further stimulation." (PMID 33574809, 2020). "The authors studied 60 patients with liver cirrhosis; 27 patients suffered from nonviral liver disease, and the remaining 33 patients were diagnosed with chronic hepatitis B or C. The majority of patients showed an abnormal low T-cell count with a mean of 492 CD4+ T-cells per μl whole blood." (PMID 30930689, 2019). "In contrast, BE from HBV-CLD patients (p = .004), especially those without liver cirrhosis (p = .003), significantly provoked the expansion of T helper 17 cells (Th17 (CD3+CD4+IL-17A+)) compared to HCs (Figure 6aand c)." (PMID 36519342, 2023). "For example, one of the features distinguishing responders from the non-responder was decreased CD4:CD8 ratios, which is known to be lower in liver cirrhosis due to lower CD4 counts." (PMID 34831456, 2021). "Having observed a decrease in CD8+ T cell frequencies and a shift of CD8+ and CD4+ T cells towards effector cells in patients with compensated but not decompensated liver cirrhosis, we next wanted to investigate the phenotype of CD8+ and CD4+ T cells in more detail." (PMID 41028194, 2025). "Moreover, CD4+ and CD8+ T cells exhibited a shift towards a more differentiated phenotype in compensated, but not decompensated liver cirrhosis." (PMID 41028194, 2025).